PTRH1 (peptidyl-tRNA hydrolase 1 homolog)
Description:
Peptidyl-tRNA hydrolase that cleaves nascent chains-tRNAs that are not stably fixed in the P-site of 60S ribosome-nascent chain complexes. Acts downstream of the ribosome-associated quality control (RQC) pathway to release non-ubiquitinated nascent chains from 60S and 80S ribosome-nascent chain complexes. Does not act on ubiquitinated nascent chains, which are cleaved by ANKZF1 for degradation.
Synonyms: C9orf115; PTH1
Tractability: No criterion of Open Targets' tractability assessment is met for any kind of drug.
Gene: Protein-coding gene on chromosome 9 (127,690,348 to 127,724,873, reverse strand). Ensembl gene ENSG00000187024.
Gene Ontology:
Molecular function: peptidyl-tRNA hydrolase activity; protein binding; RNA binding
Biological process: rescue of stalled ribosome
Cellular component: mitochondrion
Genetic constraint (gnomAD): Loss-of-function variants: 14 observed, 15.63 expected, observed/expected ratio (o/e) 0.9, 90% interval 0.59 to 1.4. The upper end of that interval is the gene's LOEUF score, 1.4, which puts it in group 5 of 6, group 1 being the genes least tolerant of losing a copy. Missense variants: 316 observed, 262.13 expected, observed/expected ratio (o/e) 1.21, 90% interval 1.1 to 1.32. Synonymous variants: 139 observed, 116.23 expected, observed/expected ratio (o/e) 1.2, 90% interval 1.04 to 1.38.
Homologues: Orthologues: chimpanzee PTRH1 (100% identical), rabbit PTRH1 (88% identical), pig PTRH1 (87% identical), dog PTRH1 (81% identical), guinea pig PTRH1 (81% identical), mouse Ptrh1 (79% identical), rat Ptrh1 (65% identical), macaque PTRH1 (59% identical), tropical clawed frog ptrh1 (52% identical), zebrafish ptrh1 (47% identical).
Diseases named in the same sentence as PTRH1 in open-access papers:
PTRH1 is named in the same sentence as 7 diseases in open-access papers, as found by Europe PMC text mining. Sharing a sentence is not in itself a finding about the gene and the disease. The quoted sentences say what the papers report.
pancreatic cancer (2 papers, 2023 to 2025). "Postoperative specimens were used to identify the expression of PD-L1 and PTRH1 in pancreatic cancer." (PMID 37434177, 2023). "Our results revealed that a high dose of glucose enhanced the stability of the PD-L1 mRNA in pancreatic tumor cells by downregulating PTRH1 through RAS signaling pathway activation following epidermal growth factor receptor (EGFR) stimulation." (PMID 37434177, 2023). "We investigated the function of PTRH1 in regulating PD-L1 expression in pancreatic cancer cells." (PMID 37434177, 2023). "Moreover, overexpression of PTRH1 reversed PD-L1 protein expression in pancreatic tumor cells when cultured in 25 mM sugar medium under the combined inhibition of STAT3 and PI3K phosphorylation." (PMID 37434177, 2023). "To examine the expression of PTRH1 in pancreatic cancer, we collected 16 cases of paired PDAC and adjacent tissue samples during surgery and identified the expression of PTRH1 and PD-L1 protein." (PMID 37434177, 2023). "we confirmed that PTRH1, as an RBP, plays a key role in PD-L1 regulation by high glucose and is closely related to anti-tumor immunity in the pancreatic cancer microenvironment." (PMID 37434177, 2023). "Peptidyl-tRNA hydrolase 1 homolog (PTRH1), another inhibitory RBP, suppressed PD-L1 expression by binding to the 3'-UTR of PD-L1 mRNA, thereby enhancing CD8+ T cell infiltration and improving their cytotoxic efficacy in pancreatic cancer." (PMID 39718205, 2025). "We established a diabetes model in C57 mice and implanted an orthotopic pancreatic tumor when the mice blood glucose reached the standard of diabetes (> 11.1 mmol/l) to describe the different immune landscapes of the pancreatic TME with different blood levels and PTRH1 expression." (PMID 37434177, 2023).
colon adenocarcinoma (1 paper, 2023). "In fact, in cancers with frequent KRAS mutations, including PDAC, lung adenocarcinoma (LAUD) and colon adenocarcinoma (COAD), PTRH1 mRNA expression was significantly negatively correlated with KRAS mRNA levels." (PMID 37434177, 2023).
diabetes (1 paper, 2023). "Further clinical studies are necessary to elucidate the association between PTRH1 expression and diabetes." (PMID 37434177, 2023). "The PTRH1 mRNA level was found to be lower in PDAC samples from patients with diabetes from TCGA (n = 146), and the same was true when comparing neoplastic epithelial cells in PDAC single-cell sequencing data (n = 24) (GSA: CRA001160)." (PMID 37434177, 2023). "According to our results, PDAC samples with diabetes (n = 7) had lower levels of PTRH1 (p value = 0.064) and significantly more PD-L1 (p value = 0.034) than those without diabetes (n = 9)." (PMID 37434177, 2023).
Hyperglycemia (1 paper, 2023). An increased concentration of glucose in the blood. "Within the hyperglycemia mice, PTRH1 overexpression was more effective than anti-PD-L1 therapy in tumor suppression, and the combination of which exerted a substantial synergistic effect." (PMID 37434177, 2023). "Separately, overexpression of PTRH1 significantly reduced the growth of implanted tumors in hyperglycemia group (p value < 0.01)." (PMID 37434177, 2023).
tumor (2 papers, 2020 to 2023). "In mice with complete immunity, PTRH1 overexpression inhibited tumor growth and significantly increased the infiltration and function of T cell." (PMID 37434177, 2023). "Next, we demonstrated the potential of PTRH1 to improve anti-tumor immunological effects in the pancreatic TME." (PMID 37434177, 2023). "PTRH1 was found to be significantly overexpressed in patients with deeper tumor infiltration." (PMID 33193701, 2020). "PTRH1, an RBP, plays a key role in the regulation of PD-L1 by high glucose and is closely related to anti-tumor immunity in the pancreatic TME." (PMID 37434177, 2023). "PTRH1 expression was not significantly different between the CRC tumor tissues and normal tissues." (PMID 33193701, 2020).
PTRH1 also shares sentences with these, for which no sentence is quoted: cancer (2 papers); lung adenocarcinoma (1).